MOG (myelin oligodendrocyte glycoprotein)
Diseases named in the same sentence as MOG in open-access papers (continued):
Sharing a sentence is not in itself a finding about the gene and the disease.
demyelination (continued). "MOG-Abs are present in more than 30% of children who present with an initial episode of demyelination, in more than 50% of those presenting with ADEM, and in almost all those with multiphasic ADEM (MDEM)." (PMID 30671648, 2019). "It has previously been shown that injection of monoclonal antibody against MOG into Lewis rats with EAE induced demyelination." (PMID 28646890, 2017). "Previously, we showed that anti-MOG antibodies are present in about 25% of pediatric patients with a first episode of acute demyelination and that these antibodies correlate with the disease course." (PMID 25889963, 2015). "An 11‐center Korean study evaluating paired serum and CSF of 474 patients with demyelination identified a CSF‐restricted MOG‐IgG profile in 4/31 (13%) patients with MS, and 9/217 (4%) patients with seronegative demyelination thought to be consistent with MOGAD." (PMID 39073255, 2024). "Therefore, many scholars believe that for children with early demyelination, early detection of MOG-Ab titers and continuous MOG-Ab monitoring and follow-up in the later period have important clinical guiding significance." (PMID 36401212, 2022). "The association of MOG antibodies with combined central and peripheral demyelination (CCPD) is not clear." (PMID 36601183, 2022). "One-third of children were positive for anti-MOG antibodies at the time of incident demyelination." (PMID 31545352, 2020). "Although many patients report prodromal illnesses, no specific viruses have been linked to MOG-related demyelination." (PMID 30671648, 2019). "Selected samples reactive to either human MOG or rodent MOG were subsequently tested for their ability to induce complement-mediated damage in murine organotypic brain slices or enhance demyelination in an experimental autoimmune encephalitis (EAE) model in Lewis rats." (PMID 29070051, 2017). "Likewise, although the presence of different CSF cytokines and chemokines has previously been investigated in NMO, CSF cytokine studies in MOG-associated demyelination are lacking." (PMID 26919719, 2016). "The CSF cytokine and chemokine levels were higher in both MOG Ab POS and MOG Ab NEG demyelination groups compared to controls." (PMID 26919719, 2016). "CSF cytokine/chemokine concentrations (median and range) in MOG Ab POS, MOG Ab NEG demyelination groups and controls according to T and B cell subsets." (PMID 26919719, 2016). "As a positive control and to further confirm the validity of this splenocyte-induced demyelination model, the ability of FTY720 in attenuating demyelination induced by MOG-splenocytes was examined." (PMID 24911000, 2014). "The patient's condition progressed and aggravated after treatments, new multiple bilateral lesions in both cerebral hemispheres indicating that the diagnosis was perhaps CNS demyelination, MBP in the serum and cerebrospinal fluid were elevated, and MOG antibody in serum was positive." (PMID 39220233, 2024). "Some previous reports have described cortical encephalitis and meningoencephalitis without demyelination and positive results for anti-MOG antibodies." (PMID 36532000, 2022). "Detailed demographic and clinical characteristics of 18 patients having MOG antibody-positive pediatric autoimmune encephalitis without demyelination." (PMID 36532000, 2022). "Immunization with MOG peptide, i.e., induction of EAE during CPZ-induced demyelination resulted in microglia activation in contrast to classic EAE, and also potentiated gene expression of CXCL10, CCL2, and CCL3 in the corpus callosum beside additional brain areas." (PMID 32582192, 2020). "Therefore, in this study, we assessed the cases of 18 children having MOG antibody-positive AE without demyelination in a single center in southwest China." (PMID 36532000, 2022). "Approximately half of seronegative NMOSD is MOG-Ig seropositive and one in five of non-NMOSD/non-MS demyelination is MOG-IgG positive." (PMID 28840314, 2017).
CNS demyelinating diseases (49 papers, 2011 to 2026). "Myelin oligodendrocyte glycoprotein antibody–associated disease (MOGAD) is defined as a demyelinating disorder of the central nervous system (CNS) linked to myelin oligodendrocyte glycoprotein antibodies (MOG-IgG)." (PMID 41459522, 2025). "The second category is ‘other demyelinating diseases of the CNS’, which includes diagnoses such as myelin oligodendrocyte glycoprotein antibody–associated disease where the host immune system attacks myelin in the brain, optic nerve and spinal cord." (PMID 39659973, 2024). "Myelin oligodendrocyte glycoprotein-IgG-associated disorder is currently recognized as an independent demyelinating disease of the CNS." (PMID 35370624, 2022). "The current limited clinical benefit of rituximab despite successful CD19+ B-lymphocyte depletion in combination with a lower risk of SIEs among patients pertaining to the MOG+ group lend further support to the recent recognition of MOGAD as a distinct CNS demyelinating disease." (PMID 38256489, 2024). "Besides clear differences in clinical and laboratory findings, MRI also provides a useful means of discriminating MOG antibody-associated disorders from other CNS demyelinating diseases, in particular MS." (PMID 30555462, 2018). "Myelin oligodendrocyte glycoprotein (MOG) antibody-associated disease refers to a clinical and radiological spectrum of demyelinating disorders of the Central Nervous System." (PMID 39479094, 2024). "The use of IVIG is more common in other CNS demyelinating diseases, such as MS, as compared to MOG-AD." (PMID 35958613, 2022). "By comparing this clearly distinct cohort to AQP-4+ NMO as well as MS, we propose that MOG+ CNS demyelinating disease represents a distinct novel disease entity." (PMID 31870389, 2019). "In the future, therefore, we recommend abstaining from generally referring to NMO, BCS, MOG-EM and MDS as “variants of MS”—a wording still found in many neurological textbooks and in many review articles on demyelinating diseases of the CNS." (PMID 30819213, 2019). "Initial work using assays with MOG in its native conformational form gave the first clue that MOG-IgG may represent a biomarker of an inflammatory CNS demyelinating disease distinct from MS." (PMID 32048003, 2020). "The common atypical ON cases, characterized by biomarkers such as aquaporin-4 (AQP4) and myelin oligodendrocyte glycoprotein (MOG) antibodies, represents distinct CNS demyelinating diseases." (PMID 40606143, 2025). "Myelin oligodendrocyte glycoprotein antibody disorders (MOGAD) have evolved as a distinct group of inflammatory, demyelinating diseases of the CNS." (PMID 35401390, 2022). "The serum was negative for antibodies associated with CNS demyelinating diseases, such as antibodies to aquaporin 4 (AQP-4), glial acidic fibrillary protein (GFAP), and myelin oligodendrocyte glycoprotein (MOG)." (PMID 38953026, 2024). "MOG-IgG is a biomarker for patients with CNS demyelinating diseases that have distinct demographic, serologic, clinical, and radiologic features from classical MS and from AQP4-IgG-mediated NMOSD, suggesting that MOG-IgG might mediate a distinct disease." (PMID 33281728, 2020). "Currently, MOG-AD is diagnosed when a patient presents with an accepted clinical demyelinating syndrome, has positive detection of MOG-IgG in serum by a validated assay, and does not fulfill criteria for another CNS demyelinating disease." (PMID 35795797, 2022). "Based on these results, and those obtained by other authors, anti-MOG antibodies would not be adequate biomarkers for the diagnosis or prognosis of MS, but rather for its differential diagnosis with MOG+-CNS demyelinating disease representing a new distinct disease entity." (PMID 34638664, 2021).
CNS demyelinating diseases (continued). "Therefore, we decided to investigate the frequency and titer levels of IgG antibodies to MOG and AQP4 in a multicenter study of patients with CNS demyelinating diseases using a live cell staining immunofluorescence assay with HEK-293A cells transfected with either AQP4 or MOG." (PMID 22204662, 2011).
COVID-19 (43 papers, 2020 to 2025). A disease caused by infection with severe acute respiratory syndrome coronavirus 2. "Few of them were associated with COVID-19-related vaccines associated with serum antibodies against myelin oligodendrocyte glycoprotein (MOG)." (PMID 39871843, 2024). "The mean time from COVID-19 to ON onset was shorter in patients with MOG-ON compared to patients with AQP4-ON (6.87 ± 6.25 weeks vs. 11.06 ± 5.84 weeks; p = 0.038), indicating a closer temporal association between MOG-ON onset and COVID-19." (PMID 38988608, 2024). "This makes it difficult to determine the exact association between COVID-19 and both MOG-ON and AQP4-ON, as well as their actual prevalence and distinctive characteristics." (PMID 38988608, 2024). "Multivariate analysis pinpointed AVDs (OR = 15.21, p = 0.043) and bilateral involvement (OR = 25.15, p = 0.015) as independent factors related to COVID-19 associated MOG-ON, with both being good discriminators for PCRON (AUC = 0.879)." (PMID 38988608, 2024). "This scarcity results in limitations in multivariate analyses aimed at ruling out confounding factors, establishing a causal link between COVID-19 and MOG-ON/AQP4-ON, and understanding the underlying pathogenesis and prognosis." (PMID 38988608, 2024). "Another interesting finding in our review was the presence of MOG antibody-associated disorder (MOGAD) in two cases following COVID-19 vaccination." (PMID 37427078, 2023). "We report a case of acute optic neuritis (ON) associated with myelin oligodendrocyte glycoprotein (MOG) antibody possibly induced by COVID-19." (PMID 34106635, 2021). "This case highlights a possible causal association between inflammation due to COVID-19 and a relapse of MOG-IgG associated disease." (PMID 33324337, 2020). "A synthesis of currently reported COVID-19-associated ON cases reveals several consistent trends: we found that MOG-ON was the most common subtype among COVID-19-associated ON cases, while AQP4-ON remained rare and the majority of patients had favorable outcomes." (PMID 40728559, 2025). "Although the exact mechanism linking COVID-19 vaccination to MOG antibody-associated disease remains unclear, the potential for vaccines to unmask or trigger autoimmune processes warrants further research." (PMID 40026947, 2025). "In examining the clinical features of patients with MOG-ON potentially linked to COVID-19, a key distinction from typical MOG-ON cases was noted: both genders were affected at a similar rate, and there was a greater likelihood of the condition affecting both eyes." (PMID 38988608, 2024). "Mild COVID-19 is more likely associated with MOG-ON than AQP4-ON." (PMID 38988608, 2024). "However, research exploring the connection between COVID-19 and ON linked to antibodies against MOG Immunoglobulin G (IgG) (MOG-ON) and AQP4 IgG (AQP4-ON) is limited." (PMID 38988608, 2024). "This suggests that the abnormality of the antiphospholipid antibody spectrum in patients with COVID-19-related MOG-ON may arise from underlying vascular endothelial damage." (PMID 38988608, 2024). "Further follow-up is needed to assess patients’ outcomes and recurrence rates, in order to determine whether COVID-19 associated MOG-ON has unique clinical features." (PMID 38988608, 2024). "Our case indicated that COVID-19 might trigger an autoimmune response that leads to MOG antibody-associated ON, similar to other pathogens that were reported in the past." (PMID 34106635, 2021). "Neurological manifestations in COVID-19 patients have been associated with the presence of autoantibodies against contactin-associated protein 2 (anti-Caspr2), GD1b ganglioside (anti-GD1b), myelin oligodendrocyte glycoprotein (anti-MOG), and myelin basic protein (anti-ObM)." (PMID 41009363, 2025). "In the multifactorial analysis, vascular disease and its risk factors superseded abnormalities in antiphospholipid antibody spectrum as independent related factors for COVID-19-related MOG-ON." (PMID 38988608, 2024).
COVID-19 (continued). "Thirdly, the proportion of patients with bilateral eye involvement was high: 66.7% of the MOG-ON patients who developed symptoms within 6 weeks after COVID-19 had bilateral eye involvement, while only 9.1% of the other MOG-ON patients had this feature." (PMID 38988608, 2024). "We perform a comparative analysis to examine the influence of COVID-19 on the development of MOG-ON and AQP4-ON, as well as to identify distinctive features associated with COVID-19-related ON." (PMID 38988608, 2024). "In terms of history of preceding infection, a higher proportion of MOG-ON patients reported a history of COVID-19 or other infections within 6 weeks prior to the onset of ON compared to the AQP4-ON group (19/26 [73.1%] vs. 6 /20 [30%]; p = 0.007)." (PMID 38988608, 2024). "With the widespread outbreak of COVID-19, studies have reported cases of isolated ON following COVID-19 infection in patients who were seropositive for MOG-Ab and AQP4-Ab." (PMID 38988608, 2024). "The IgG anti-MOG antibodies were strongly positive, and the anti-spike protein COVID-19 antibodies were increased." (PMID 37257164, 2023). "In both cases, patients developed neurological symptoms after receiving a COVID-19 vaccine, and their MRI findings revealed hyperintense lesions in different brain regions with MOG-antibody positivity." (PMID 37427078, 2023). "It was seen that “COVID-19”, “neuroinflammation”, and “myelin oligodendrocyte glycoprotein” were keywords that frequently appeared more recently, suggesting that they will be future research hotspots." (PMID 37346048, 2023). "Multiple types of exanthema are described in the literature, including urticarial, petechial, and varicella-like rash with central nervous system vasculopathy with anti-myelin oligodendrocyte glycoprotein antibodies in patients with COVID-19." (PMID 36979849, 2023). "After optic and systemic examination, the patient was diagnosed with MOG antibody-positive ON possibly induced by COVID-19 and was admitted to our hospital." (PMID 34106635, 2021). "This is the first rare case report of COVID-19-related optic perineuritis in critically ill COVID-19 patients with seronegative MOG antibody." (PMID 34712522, 2021). "Comorbidities such as hypertension, diabetes, and AVDs may have a synergistic effect on MOG-ON in patients with COVID-19, which warrants further investigation." (PMID 38988608, 2024). "Whether COVID-19 and pregnancy/delivery interact to influence the development of MOG-ON and AQP4-ON requires further investigation with larger cohorts." (PMID 38988608, 2024). "Our study, consistent with previous investigations, indicated that SARS-CoV-2 infection may trigger the production of MOG-Ab and the onset of an immune-mediated ON in COVID-19 cases." (PMID 38054007, 2023). "Our study showed that levels of several autoantibodies to nervous system epitopes were associated with the clinical severity of COVID-19, including IgG antibodies to the dopamine 1 receptor, NMDA receptors, brain-derived neurotrophic factor (BNDF), and myelin oligodendrocyte glycoprotein." (PMID 36832180, 2023). "MOG antibodies are present in the serum of some patients with COVID-19 vaccine-related ADEM." (PMID 37376503, 2023). "Antibodies against NMDA receptors (IgG), BDNF (IgG), GAD-65 (IgG), D1 receptor (IgG), and myelin oligodendrocyte glycoprotein (IgG) were elevated in patients with severe COVID-19 and those who required supplemental oxygen compared with those with mild COVID-19." (PMID 36832180, 2023). "Notably, dysregulated serum levels of autoantibodies NMDAR, GAD65, and MOG were detected in patients with severe COVID-19 compared with healthy controls and mild COVID-19 patients." (PMID 38138047, 2023). "The patient was diagnosed with MOG antibody-positive acute ON possibly induced by COVID-19." (PMID 34106635, 2021). "COVID-19 was confirmed by nasopharyngeal swab and MOG-IgG serological reversion was noted." (PMID 33324337, 2020).
COVID-19 (continued). "A less likely but possible pathway for the generation of MOG-Ab may involve the incidental unveiling of MOG protein to the immune system’s antigen-presenting cells during inflammation in the CNS’s white matter or optic nerve, instigated by COVID-19." (PMID 39081310, 2024). "This would offer insight into whether COVID-19 associated ON presents distinct traits or is merely a usual manifestation of post-infection MOG-ON, considering that MOG-ON/MOGAD might be linked to non-specific viral infections." (PMID 38988608, 2024). "However, it has also been pointed out that despite auto-antibodies targeting MOG, molecular mimicry is unlikely the cause due to lack of homology between the COVID-19 viral protein and the MOG protein." (PMID 38299114, 2024). "Indeed, both MOG and NMDAR1, which presented significant linear and three-dimensional overlap with spike, have been associated with COVID-19 in a more expressive way than the other autoimmune affection and have been related to COVID-19 vaccination." (PMID 38138047, 2023). "Recent studies reveal elevated levels of brain-reactive autoantibodies against MBP, MOG, tubulin, CP2, and synaptophysin in patients suffering from protracted COVID-19, suggesting a possible involvement of neuroautoimmune pathophysiology." (PMID 38560433, 2024). "In COVID-19-associated ON, all serum samples were negative for AQP4 and GFAP antibodies, four (33.3%) patients were MOG-IgG-positive (titres were 1:100 in three patients and 1:32 in one patient), and one patient was CRMP5-IgG-positive (titre, 1:10)." (PMID 40728559, 2025). "These trends align with our own findings in the COVID-19-positive ON subgroup, where MOG-ON accounted for 33.3% (4/12) and no cases of AQP4-ON were observed." (PMID 40728559, 2025). "In ON without COVID-19, seven (16.3%) patients were MOG-IgG-positive, 16(37.2%) were AQP4-IgG-positive, and the remaining patients were both negative." (PMID 40728559, 2025). "We consider it encouraging that all 3 patients with MOG antibody-positive ON induced by COVID-19 had not worsened or presented with symptoms of respiratory illness during the treatment period of systemic steroids." (PMID 34106635, 2021). "Cluster 5, which includes genes at 6p22.1 (HLA-A, HCG4P5, HLA-T, MOG, TRIM26, HCG9, IFITM4P), demonstrated further connections between JIA and a subset of autoimmune/inflammatory traits (i.e., type 1 diabetes, asthma, eczema, and severe COVID-19 or rheumatoid arthritis)." (PMID 39175752, 2024). "Interestingly, MOG-IgG levels were significantly higher after non-COVID infections than after COVID-19." (PMID 38576796, 2024). "The termination of the dynamic zero COVID-19 strategy and the subsequent resurgence of COVID-19 in China led to a marked increase in ON and provided us a chance to investigate the prevalence of serum AQP4-Ab and MOG-Ab in ON patients after SARS-CoV-2 infection." (PMID 38054007, 2023).